SULT2A1 (sulfotransferase family 2A member 1)
Description:
Sulfotransferase that utilizes 3'-phospho-5'-adenylyl sulfate (PAPS) as sulfonate donor to catalyze the sulfonation of steroids and bile acids in the liver and adrenal glands. Mediates the sulfation of a wide range of steroids and sterols, including pregnenolone, androsterone, DHEA, bile acids, cholesterol and as well many xenobiotics that contain alcohol and phenol functional groups. Sulfonation increases the water solubility of most compounds, and therefore their renal excretion, but it can also result in bioactivation to form active metabolites. Plays an important role in maintening steroid and lipid homeostasis. Plays a key role in bile acid metabolism, mediating formation of 3-sulfated bile acids. In addition, catalyzes the metabolic activation of potent carcinogenic polycyclic arylmethanols (By similarity).
Synonyms: ST2A1; DHEA-ST; DHEA-ST8; HST; STD; DHEAS; ST2; ST2A3; SULT2A3; hSTa
Tractability: Small molecule: a structure with a bound ligand is known; a high-quality ligand is known; it has a high-quality binding pocket. PROTAC: its protein half-life has been measured; a small molecule that binds it is known.
Target class: Enzyme; Transferase
Gene: Protein-coding gene on chromosome 19 (47,870,467 to 47,886,347, reverse strand). Ensembl gene ENSG00000105398.
Subcellular location: Cytoplasm
Subcellular location (Human Protein Atlas): Cytosol
Pathways (Reactome):
Metabolism: Cytosolic sulfonation of small molecules; PPARA activates gene expression
Drug ADME: Paracetamol ADME
Gene Ontology:
Molecular function: 3'-phosphoadenosine 5'-phosphosulfate binding; alcohol sulfotransferase activity; bile-salt sulfotransferase activity; protein binding; steroid sulfotransferase activity; sulfotransferase activity
Biological process: 3'-phosphoadenosine 5'-phosphosulfate metabolic process; bile acid metabolic process; cholesterol metabolic process; ethanol catabolic process; sensory perception of itch; steroid metabolic process; sulfation; thyroid hormone metabolic process; xenobiotic metabolic process; sulfur compound metabolic process
Cellular component: cytoplasm; cytosol
Genetic constraint (gnomAD): Loss-of-function variants: 39 observed, 31.59 expected, observed/expected ratio (o/e) 1.23, 90% interval 0.95 to 1.61. The upper end of that interval is the gene's LOEUF score, 1.61, which puts it in group 6 of 6, group 1 being the genes least tolerant of losing a copy. Missense variants: 273 observed, 325.67 expected, observed/expected ratio (o/e) 0.84, 90% interval 0.76 to 0.93. Synonymous variants: 115 observed, 108.28 expected, observed/expected ratio (o/e) 1.06, 90% interval 0.91 to 1.24.
Homologues: Orthologues: chimpanzee SULT2A1 (98% identical), macaque SULT2A1 (89% identical), rabbit SULT2A1 (68% identical), pig SULT2A1 (66% identical), mouse Sult2a7 (65% identical), mouse Sult2a1 (64% identical), mouse Sult2a6 (64% identical), mouse Sult2a3 (63% identical), mouse Sult2a5 (63% identical), guinea pig Std1 (63% identical), mouse Sult2a4 (63% identical), rat Sult2a2 (62% identical), and 19 more. Paralogues in human: SULT2B1 (48% identical), SULT1B1 (39% identical), SULT1C2 (38% identical), SULT1A3 (38% identical), SULT1A4 (38% identical), SULT1A2 (37% identical), SULT1C4 (37% identical), SULT1A1 (36% identical), SULT1E1 (36% identical), SULT1C3 (35% identical), SULT6B1 (31% identical), SULT4A1 (30% identical).
Diseases named in the same sentence as SULT2A1 in open-access papers:
SULT2A1 is named in the same sentence as 120 diseases in open-access papers, as found by Europe PMC text mining. Sharing a sentence is not in itself a finding about the gene and the disease. The quoted sentences say what the papers report.
hyperandrogenism (19 papers, 2010 to 2025). Excessive secretion of androgens from the adrenal glands or gonads. "SULT2A1 codes for a protein, which catalyzes the sulfation of steroids and bile acids in the liver and adrenal glands, and may have a role in the inherited adrenal androgen excess in women with polycystic ovary syndrome." (PMID 25400620, 2014).
cholestasis (11 papers, 2014 to 2025). Impairment of the bile flow caused by obstruction within the liver, or outside the liver in the bile duct system. "Taking into account the biological importance of SULT2A1 in protecting against the dysregulation of homeostasis caused by cholestasis, we considered that it is worthy to study its expression." (PMID 26504856, 2015). "SULT2A1 is predominantly expressed at higher levels in female mouse livers, and bile acid accumulation in cholestasis has been shown to induce SULT2A1 via PXR activation." (PMID 36737039, 2023). "FXR, also known as NR1H4, can be activated by BA, especially CDCA, DCA, and LCA, and plays an important role in SULT2A1 expression in liver and a protective role in maternal cholestasis induced damage and oxidative stress." (PMID 31443432, 2019). "Meanwhile, we found that the expression of SULT2A1 was enhanced by EE treatment, which may result from the increase in the compensatory metabolism of bile acid in the liver due to cholestasis." (PMID 34064649, 2021). "In this study, we demonstrate that arbutin has a protective effect on α-naphthylisothiocyanate–induced cholestasis via upregulation of the levels of FXR and downstream enzymes associated with bile acid homeostasis such as Bsep, Ntcp, and Sult2a1, as well as Ugt1a1." (PMID 34926449, 2021). "The genes regulated in all pathways, Cyp1a1, Cyp1a2, Cyp2a1, Cyp2b1, Cyp4a8, Cyp2c11, Rdh16, Alox15, Ephx2, Sult2a1, and Acox2, were the potential targets for ZYP treatment of cholestasis." (PMID 37881184, 2023). "Acox2 and Sult2a1 are essential genes in PPAR signaling and bile secretion, and studies have revealed a correlation between the expression of these genes and cholestasis." (PMID 37881184, 2023). "To test our hypothesis, we analyzed the levels of PXR and its target gene SULT2A1 in PSC and PBC patients with comparable degrees of clinical cholestasis and sought out for potentially significant differences amongst PSC and PBC in this regard." (PMID 26504856, 2015). "In human cholestasis, elevated VDR may up-regulate levels of bile acids transporters (e.g. MRP3), but not induce detoxification enzymes (e.g. SULT2A1)." (PMID 25798860, 2015).
depression (10 papers, 2009 to 2022). "Bile salt sulfotransferase 1 (SULT2A1) was associated with inflammation response, immune regulation and lipid metabolism in patients with major depressive disorder." (PMID 32372980, 2020).
breast carcinoma (9 papers, 2004 to 2025). "Thus, high ERRα expression in breast cancer by enhancing SULT2A1 activity could also support breast cancer cell resistance to anti-hormonal therapy." (PMID 30254608, 2018). "We also observed suggestive association for UGT2B11 in breast and endometrial cancer as well as for HSD11B1, SULT2A1 and SULT2B1 in breast cancer." (PMID 20617168, 2010).
diabetes (6 papers, 2010 to 2024). "Specifically, Pstpip1, Il18r1, Sult2a1 overlapped the QTLs of “Non-insulin dependent diabetes mellitus (Niddm)”." (PMID 21124896, 2010).
endometriosis (5 papers, 2022 to 2025). The growth of functional endometrial tissue in anatomic sites outside the uterine body. "There has been limited research on the roles of ACSL5, PLA2G4A, EHHADH, GPAM, PLA2G15, SULT2A1, and ACSL3 in endometriosis, highlighting the necessity for further investigation to elucidate their contributions to its pathogenesis." (PMID 40527850, 2025).
prostate carcinoma (4 papers, 2019 to 2022). A carcinoma that arises from epithelial cells of the prostate gland. "Interestingly, we note that LXR activation might increase SULT2A1 mRNA levels in human LNCaP prostate cancer cells based on previous research, and the formation of a range of oxysterol sulfates shows antagonistic effects on LXRs." (PMID 35599597, 2022).
endometrial cancer (3 papers, 2010 to 2023). Primary or metastatic malignant neoplasm involving the endometrium (mucous membrane that lines the endometrial cavity). "As SULT2A1 is not expressed in either endometrial cancer or adjacent control endometrium, SULT2B1 is the major DHEA-specific SULT enzyme in endometrial cancer, and increased SULT2B1 expression has recently been reported in endometrial cancer, compared to adjacent control endometrium." (PMID 26924986, 2016).
hepatocellular carcinoma (3 papers, 2013 to 2022). A malignant tumor that arises from hepatocytes. "SULT2A1 expression is down-regulated in hepatocellular carcinoma and correlated with higher grade and stage of cancer." (PMID 23874324, 2013).
Cholestatic liver disease (2 papers, 2019 to 2022). "Activation of PPARα had a beneficial effect on cholestatic liver diseases, and was mainly involved in the inhibition of CYP7A1 and upregulation of CYP3A4, UGT1A, and SULT2A1, and induction of MDR2 to increase biliary phospholipids secretion." (PMID 30774596, 2019).
Crohn ileitis (2 papers, 2018 to 2020). A Crohn disease involving a pathogenic inflammatory response in the ileum. "In this regard, “mRNA expression levels of ASBT, breast cancer-related protein (BCRP), sulfotransferase family 2A member 1 (SULT2A1), and fibroblast growth factor 19 (FGF-19) were significantly lower in inflamed regions in patients with active Crohn’s ileitis than in controls”." (PMID 32595517, 2020). "In the study, mRNA expression levels of ASBT, breast cancer-related protein (BCRP), sulfotransferase family 2A member 1 (SULT2A1), and fibroblast growth factor 19 (FGF-19) were significantly lower in inflamed regions in patients with active Crohn's ileitis than in controls." (PMID 30402511, 2018).
liver disease (2 papers, 2015 to 2023). "More research is needed to understand the enigmatic role of SULT2A1 in the development of liver disease." (PMID 26504856, 2015). "Besides, SOX17, SULT2A1, and BLVRA have potential roles to play in other liver diseases." (PMID 36777627, 2023).
alcoholic cirrhosis (1 paper, 2015). "Analysis of human livers from various chronic liver diseases such as PBC, PSC, autoimmune hepatitis, and alcoholic cirrhosis (but not in cryptogenic cirrhosis) has shown that SULT2A1 activity and concentration are significantly reduced when compared to normal livers." (PMID 26504856, 2015).
attention deficit-hyperactivity disorder (1 paper, 2017). A disorder characterized by a marked pattern of inattention and/or hyperactivity-impulsivity that is inconsistent with developmental level and clearly interferes with functioning in at least two settings (e.g. at home and at school). "This study examined the relationships among polymorphisms of the STS gene and SULT2A1 gene, dehydroepiandrosterone (DHEA) and its sulfated form (DHEA-S), and characteristics of attention-deficit/hyperactivity disorder (ADHD)." (PMID 28367959, 2017).
breast tumor (1 paper, 2018). "In breast tumor tissue, steroid sulfation is catalyzed by SULT1E1, SULT1A1, and SULT2A1." (PMID 30042681, 2018).
Cirrhosis (1 paper, 2022). A chronic disorder of the liver in which liver tissue becomes scarred and is partially replaced by regenerative nodules and fibrotic tissue resulting in loss of liver function. "Eight independent prognostic parameters, including α‐fetoprotein, alanine aminotransferase, gender, age, cirrhosis, expression of SULT2A1, tumor stage, and relapse, were enrolled in the prediction model." (PMID 35599597, 2022).
Nephroblastoma (1 paper, 2023). An embryonal neoplasm characterized by the presence of epithelial, mesenchymal, and blastema components. "To study cortex zonation in more detail, we used nephroblastoma overexpressed/cysteine-rich protein 61/connective tissue growth factor/nephroblastoma overexpressed gene-3 (NOV, also known as CCN3) as a marker for the DZ and sulfotransferase 2A1 (SULT2A1) as a marker for the FZ." (PMID 37440461, 2023).
osteoporosis (1 paper, 2018). A condition of reduced bone mass, with decreased cortical thickness and a decrease in the number and size of the trabeculae of cancellous bone (but normal chemical composition), resulting in increased fracture incidence. "We confirmed the causal role of adrenal‐secreted sulfated steroids in osteoporosis and identified two novel genetic loci (CYP3A5 and SULT2A1) to be important in the regulation of metabolites causing osteoporosis." (PMID 29232479, 2018).
tumor (12 papers, 2015 to 2025). "Data revealed that, compared to the other two enzymes, SULT2A1 showed significant decrease in tumor tissues against normal control." (PMID 35599597, 2022). "We also analyzed the expression of SULT2A1 among different tumor grades and found that downregulation of SULT2A1 was correlated with highly malignant tumor, consistent with previous findings." (PMID 35599597, 2022). "The mRNA expression levels of SULT1A1, SULT1A3, SULT1E1, and SULT2A1 decreased or drastically decreased in 90% of the tumor samples in comparison with the matched pericarcinomatous samples." (PMID 28634336, 2017). "The activities of SULT1A1, SULT1B1, SULT1E1 and SULT2A1 in 9 of 10 samples showed a significant decrease in tumor tissues relative to matched pericarcinomatous tissues, whereas the activities of SULT1A3 in 7 of 10 samples increased." (PMID 28634336, 2017). "Thus, using probe substrates, we systematically measured the metabolic functions of SULT1A1, SULT1A3, SULT1B1, SULT1E1, and SULT2A1 in tumor S9 (tHLS9-pooled), pericarcinomatous S9 (nHLS9-pooled), and reference pooled normal human S9 (rHLS9-pooled)." (PMID 28634336, 2017). "Immunohistochemical staining of mouse tumor tissues in livers was also carried out to detect the relationship between 27‐OHC, SULT2A1, and EMT." (PMID 35599597, 2022). "Also, the expression of SULT2A1 is extremely downregulated in human HCC tissues and is correlated with poor prognosis and tumor metastasis." (PMID 35599597, 2022).
cancer (6 papers, 2013 to 2022). A tumor composed of atypical neoplastic, often pleomorphic cells that invade other tissues. "It is possible that SULT2A1 CNV polymorphism may contribute to individual variation in response to drugs that undergo sulfation as well as altered risk for cancer and other diseases." (PMID 23874324, 2013). "Interestingly, SULT2A1 mRNA was neither detected in normal nor cancer tissue in TCGA in line with nonspecific IHC staining shown in HPA." (PMID 31655797, 2019).
infection (1 paper, 2009). The state of being infected such as from the introduction of a foreign agent such as serum, vaccine, antigenic substance or organism. "Also, vaccination affects the infection-induced metabolic response with respect to SULT2A1 and CYP7A1, respectively." (PMID 19341445, 2009).
SULT2A1 also shares sentences with these, for which no sentence is quoted: Hirsutism (14 papers); hyperandrogenemia (11); acne (7); Insulin resistance (6); Obesity (6); Adrenal Hyperandrogenism (5); dementia (4); preeclampsia (4); adrenal tumors (3); Alzheimer disease (3); dyslipidemia (3); Hypertension (3); Infertility (3); Sepsis (3); Adrenal insufficiency (2); alopecia (2); androgenetic alopecia (2); autism (2); bipolar disorder (2); cardiovascular disease (2); cognitive decline (2); Cushing syndrome (2); hip fracture (2); hypercortisolemia (2); pheochromocytoma (2); Primary hypothyroidism (2); primary sclerosing cholangitis (2); sarcopenia (2); Stroke (2); type 2 diabetes (2).
A further 69 diseases each share a sentence with SULT2A1 in 1 paper.